STAT3 (signal transducer and activator of transcription 3)
Diseases named in the same sentence as STAT3 in open-access papers (continued):
Sharing a sentence is not in itself a finding about the gene and the disease.
colorectal cancer (continued). "Extensive literatures have demonstrated that Alistipes promotes the development of colorectal cancer by activating the IL-6/STAT3 signaling pathway." (PMID 38721274, 2024). "For example, miR-124, miR-125, miR-320, miR-1301 directly target 3′-UTR of STAT3 and inhibit cell cycle progression, proliferation, migration and invasion in bladder cancer, gastric cancer, lung adenocarcinoma and colorectal cancer." (PMID 38245798, 2024). "Increased STAT3 activation, as assessed by the presence of the tyrosine phosphorylation isoform of the protein, is observed in more than 50% of colorectal cancer tumours." (PMID 38600086, 2024). "C-myc is an important downstream effector of STAT3 signaling and is involved in the proliferation and migration of colorectal cancer cells." (PMID 38710698, 2024). "STAT3 is silenced in colorectal cancer cells due to epigenetic modifications (methylation), resulting in decreased expression." (PMID 39830506, 2024). "LYW-6, a novel derivative of CTS, presents better affinity and inhibition capacity for transcription factor STAT3 than CTS in the treatment of colorectal cancer, with much reduced toxicity." (PMID 39479449, 2024). "Does the STAT3/PD-1 signaling axis truly occupy a pivotal role in enhancing the oncogenic potential of colorectal cancer cells?" (PMID 38761176, 2024). "Excessive STAT3 signalling via gp130, the shared receptor subunit for IL-6 and IL-11, contributes to disease progression and poor survival outcomes in patients with colorectal cancer." (PMID 38600086, 2024). "Silencing STAT3 expression inhibits cell growth in colorectal cancer cells through G2 phase arrest, inducing apoptosis." (PMID 38720012, 2024). "The report showed TAM-secreted IL-6-induced chemoresistance by activating the IL-6R/STAT3/miR-204 pathway in colorectal cancer cells." (PMID 39247822, 2024). "Numerous studies have shown that the constitutive activation of STAT3 in colorectal cancer drives cell proliferation and tumor growth, thus providing novel insights into treating this disease." (PMID 38273295, 2024). "For this reason, therapeutic strategies that suppress STAT3 activation represent a promising approach to developing new colorectal cancer drugs." (PMID 38600086, 2024). "Apart from its role as a chemoattractant, CCL2 facilitates the immunosuppression of T cells by regulating the suppressive functions of MDSCs via STAT3 in colorectal cancer and is expressed not only by cancer cells but also by TAMs and MDSCs." (PMID 38448555, 2024). "In conclusion, succinate promotes the metastasis and invasion of colorectal cancer, and when cancer cells are specifically inhibited by a STAT3 inhibitor, the effect of succinate in promoting cancer cell metastasis and invasion is weakened." (PMID 38486162, 2024). "Interleukin-6 a pleiotropic cytokine involved in immune regulation and activation of JAK2/STAT3 pathway in colorectal cancer." (PMID 38869738, 2024). "This study further validates the role of GNAI1 in promoting angiogenesis in colorectal cancer through its influence on STAT3 activity." (PMID 39695099, 2024). "STAT3 levels were found to be especially elevated in stage I-III colorectal cancer patients undergoing surgery, leading to abnormal local and systemic inflammatory responses and poorer prognoses." (PMID 38273295, 2024). "We found that the mechanism underlying this evidence would be the tumor–stromal interaction between colorectal cancer cells and macrophages in the tumor budding area via the interleukin-6 receptor/STAT3 signaling pathway." (PMID 38486225, 2024). "Recent research showed that exosomes containing STAT3 can promote resistance to 5‐FU in colorectal cancer cells." (PMID 39475099, 2024).
colorectal cancer (continued). "Elevated miR-572 expression and downregulation of modulator of apoptosis-1 were observed in colorectal cancer with high expression of STAT3." (PMID 38273295, 2024). "To further explore the effect of 23-HBA inhibition of IL-10 release from M2 macrophages on chemotherapy resistance in colorectal cancer, we conducted an analysis of STAT3 and Bcl-2, both of which serve as key mediators within the IL-10 signaling pathway." (PMID 38554148, 2024). "SLCO1B3 can promote the proliferation and metastasis of colorectal cancer by activating the STAT3 pathway." (PMID 38710698, 2024). "For instance, a higher level of nuclear STAT5 is associated with early recurrence and decreased survival rate in prostate cancer, while STAT3 overexpression results in recurrence and poor survival in melanoma, cervical cancer, and colorectal cancer." (PMID 39136000, 2024). "Mesenchymal stem cells derived from human CRCs facilitate colorectal cancer progression via the IL-6/JAK2/STAT3 signaling pathway." (PMID 38673975, 2024). "BY4008 had been shown to mediate its antitumor effects in colorectal cancer primarily by inhibiting STAT3 signaling." (PMID 39153914, 2024). "Previous studies have shown that CCN1 activates the FAK/MEK/ERK signaling pathway in colorectal cancer by binding to integrin αVβ5 to activate STAT3, a key upstream molecule known to regulate S100A8." (PMID 39659236, 2024). "Actually, CAF-derived IL-6 and JAK/STAT3 pathway have been demonstrated to involve in treatment resistance in multiple other cancers, including pancreatic cancer, cholangiocarcinoma, colorectal cancer and breast cancer." (PMID 38311608, 2024). "In colorectal cancer, IL-22 enhances autocrine expression of IL-8 in tumor cells via STAT3 activation, assisting tumor cells survive from FOLFOX chemotherapy." (PMID 38596684, 2024). "We identified the presence of an intact gp130 signalling cascade in tumour organoids obtained from colorectal cancer patients by evaluating IL-6 and IL-11-dependent phosphorylation of STAT3." (PMID 38600086, 2024). "Specifically, FGFR2 has been identified as a driver of M2 macrophage polarization in colorectal cancer by increasing PAI-1 expression via the JAK2/STAT3 pathway." (PMID 39436561, 2024). "Meanwhile, miR-1299 was found to be a negative regulator of ST AT3 in colon cancer, which targeted deletion of miR-139-5p, activating STAT3 signaling and promoting progression of colorectal cancer, and miR-125b inhibited cell proliferation by targeting STAT3." (PMID 38967742, 2024). "The inhibition of angiogenesis, proliferation, and NF-κB/STAT3 axis in colorectal cancer by analapril can increase drug sensitivity." (PMID 39014491, 2024). "It is well‐established that both STAT3 and interleukin‐6 IL‐6 are commonly found in the tumour microenvironment of human and murine colorectal cancer, correlating with reduced survival rates and increased recurrence risks." (PMID 39495702, 2024). "Deletion of protease-activated receptor 2 (PAR2) in MDSCs promotes the progression of colorectal cancer by facilitating the production of reactive oxygen species mediated by transcription activator 3 (STAT3)." (PMID 39100676, 2024). "Significant effort has been undertaken to identify upstream activators of Signal Transducer and Activator of Transcription 3 (STAT3) and how these factors can be exploited to develop new therapies for colorectal cancer." (PMID 38600086, 2024). "SOX13 is induced by hepatocyte growth factor through the JAK2/STAT3 signaling pathway, promoting metastasis in colorectal cancer by upregulating SNAI2 and c-MET expression." (PMID 39726600, 2024). "The promotion of colorectal cancer by Chemokine (CCL2) occurs through the enhancement of polymorphonuclear (PMN)-MDSC immunosuppressive features via the STAT3 pathway." (PMID 39100676, 2024).
colorectal cancer (continued). "And the exosomal circPOLQ derived from tumor cells increases IL‐10 and STAT3 by absorbing miR‐379‐3p, thereby promoting polarization of M2 macrophages and exacerbating the occurrence of metastatic nodules in colorectal cancer." (PMID 39584047, 2024). "For instance, B-cell acute lymphoblastic leukemia relies on Akt and STAT3 pathways, colorectal cancer involves STAT3 and NF-κB pathways, and ovarian cancer stem cells necessitate the engagement of NF-κB and MAPK pathways." (PMID 38840908, 2024). "Reportedly, FGFR2 contributes to activating the JAK2/STAT3 pathway in colorectal cancer, resulting in the promotion of PD-L1 expression." (PMID 38326861, 2024). "The exploration of KIF20A has also advanced targeted therapy options, particularly in manipulating pathways such as JAK/STAT3 signaling, which are crucial for innovative treatments in colorectal cancer and other malignancies." (PMID 39272816, 2024). "For example, colorectal cancer-derived mesenchymal stem cells promoted EMT and increased the migration and invasion of colorectal cancer by activating IL-6/JAK2/STAT3 signaling." (PMID 38182570, 2024). "LXN directly targets and inhibits JAK1, which attenuates the activity of STAT3, consistent with our previous reports on colorectal inflammation and colorectal cancer in LXN knockout mice." (PMID 39424784, 2024). "Another compound, K-80003, a derivative of Sulforaphane, also inhibits colorectal cancer development through the suppression of STAT3 phosphorylation; Meloxicam is recognized as a potential inhibitor of STAT3 due to its inhibitory effects on STAT3 activation." (PMID 39598398, 2024). "On the other hand, a number of T cells, such as Th17, can secrete IL-6 and TNF-α to stimulate STAT3 and NF-κB in accelerating the proliferation and progression of colorectal cancer." (PMID 39014491, 2024). "This process activates the JAK/STAT3 signaling pathway, augmenting the overall expression of PD-L1 in colorectal cancer (CRC) cells." (PMID 38762481, 2024). "Precise elucidation of the mechanisms by which PDIA3, alongside STAT3 and the PD-1/PD-L1 axis, influences therapeutic denouements in colorectal cancer remains quintessential." (PMID 38761176, 2024). "Our further investigation revealed that CRC-EVs upregulate VEGFA by modulating the JAK/STAT3 pathway, thus promoting the angiogenesis of colorectal cancer tumors." (PMID 39596828, 2024). "In the early stage of colorectal cancer, tumor cells are highly differentiated and relatively less malignant, and their STAT3 levels are low expressed." (PMID 39830506, 2024). "Mechanistically, STAT3 increased miR-572 levels to inhibit the expression of modulator of apoptosis-1, leading to enhanced cell growth, migration, and invasion in colorectal cancer." (PMID 38273295, 2024). "On the other hand, STAT‐3 regulates the apoptosis‐related gene expression and abnormal activation of STAT‐3 in colorectal carcinomas (Gargalionis, Papavassiliou, and Papavassiliou 2021)." (PMID 39723045, 2024). "Bufalin blocked CAF-induced invasion and metastasis of colorectal cancer cells by inactivation of the STAT3 pathway." (PMID 36903477, 2023). "STAT3 is phosphorylated by members of the IL-6 family and is mainly known for the promotion of immunosuppression and its effect in colorectal cancer progression following constitutive activation." (PMID 38044939, 2023). "Hepsin overexpression increased colorectal cancer cell invasion, Erk1/2 and STAT3 phosphorylation, and thrombin generation in plasma." (PMID 37275957, 2023). "The combined effects finally contributed to p-STAT3 signaling pathway activation and colorectal cancer cell proliferation and invasion." (PMID 38001065, 2023). "In colorectal cancer, expression of RhoA is elevated and further results in induction of Tyr705 phosphorylation of STAT3." (PMID 37752569, 2023).
colorectal cancer (continued). "In colorectal cancer, FEZF1-AS1/PKM2 serves as a lncRNA/protein complex that is associated with cancer cell proliferation and metastasis by activating STAT3 signaling." (PMID 37993428, 2023). "CAF-conditioned media-treated colorectal cancer cells expressed high levels of p-STAT3 and matrix metalloproteinase-2, whereas low levels of E-cadherin were found in hyperactive STAT3-expressing cancer cells." (PMID 36903477, 2023). "The inhibitors of miRNAs-221/-222 in colorectal cancer reduced cell growth and colony formation and STAT3 and IL-6 activity." (PMID 36816749, 2023). "Chen Wei groups suggest that Stattic reduces the STAT3 phosphorylation and total STAT3 level in IL-6-stimulated HCT116 colorectal cancer cells." (PMID 37821959, 2023). "Human mesenchymal stem cells derived from colorectal cancer have been shown to promote the progression of colorectal cancer through the IL-6/JAK2/STAT3 signaling pathway." (PMID 37958803, 2023). "In particular, the colonization of P. anaerobius in CRC lesion mediated the recruitment of MDSCs into the colorectal cancer microenvironment, which secreted IL-23 and subsequently promoted chemoresistance by activating Stat3-EMT of colon cancer cells." (PMID 37781363, 2023). "Another downstream effector of TRIM6 in colorectal cancer is STAT3 (signal transducer and activator of transcription 3)." (PMID 38813007, 2023). "Depletion of STAT3 in macrophages repolarized TAMs, inhibited tumor growth, and increased the infiltration of cytotoxic T cells in an autochthonous model of colorectal cancer." (PMID 37308559, 2023). "Aberrant activation of STAT3 has been reported in many human solid tumors, including colorectal cancer." (PMID 37024465, 2023). "STAT3 siRNA-containing nanoparticles and DOX-containing nanoparticles caused the cytotoxicity of breast and colorectal cancer cells." (PMID 38067351, 2023). "STAT3 silencing in HT-29 colorectal carcinoma cells resulted in their cell cycle arrest and the inhibition of proliferation." (PMID 38067351, 2023). "It has been suggested that propofol triggers ferroptosis by reducing the expression of STAT3 in colorectal cancer cells, and that ectopic expression of STAT3 alleviates ferroptosis." (PMID 36232407, 2022). "Other TCMs, such as Wuweiwan (WMW Meiwan, WMW), reduce CAC (colitis and colorectal cancer) by regulating the balance between “tumour promoting bacteria” and “carcinoma suppressing bacteria” and the NF-kB/IL-6/STAT3 pathways." (PMID 35431939, 2022). "IL-6 enhances the proliferation of colorectal cancer cell lines in vitro, resulting in an increase in NF-kB and STAT3, which induce colorectal cancer cell growth." (PMID 36289922, 2022). "More recently, a study also reported that Grim-19 repressed hypoxia-induced invasion and epithelial-mesenchymal transition by repressing autophagy through inactivation of the STAT3/HIF-1α signaling axis in colorectal cancer." (PMID 36387896, 2022). "HSP90 is needed to cooperate with CD24 to enhance STAT3‐mediated VEGF transcription to inducing colorectal cancer angiogenesis." (PMID 35928554, 2022). "In summary, our data highlight a critical role of STAT3 activation in type I collagen-expressing fibroblasts for the growth of experimental colorectal cancer in the AOM/DSS model." (PMID 35326623, 2022). "Other research also indicated that DICER1-AS1 functioned as promoter in colorectal cancer by regulating miR-296-5p/STAT3 pathway." (PMID 35183226, 2022). "STAT3 regulates ZEB1 expression, which can participate in STAT3-induced cell invasion and E-cadherin downregulation in colorectal cancer." (PMID 36012631, 2022). "LL1 can also induce apoptosis and inhibit metastasis in colorectal cancer cells by selectively blocking STAT3 activation." (PMID 36557902, 2022). "In another study, berberine was reported to hinder the COX-2/PGE2-mediated JAK2/STAT3 signaling pathway in colorectal cancer cell invasion and metastasis." (PMID 36144625, 2022).
colorectal cancer (continued). "It has been also reported that the phosphorylated STAT3 level decreases in response to 5-FU treatment than the control levels of colorectal cancer cells." (PMID 35366874, 2022). "This study elucidated that the efficacy of anti-cancer reagent was mediated by JAK2/STAT3 signaling pathway in colorectal cancer HCT116 and SW480 cells." (PMID 35207737, 2022). "In colorectal cancer, IL-6 promoted cell proliferation and drug resistance through its downstream signaling molecules, such as STAT3, representing potential molecular targets for cancer therapy." (PMID 36091805, 2022). "The IL-6-mediated STAT3 signaling pathway is the main target for the treatment of colorectal cancer and IBD." (PMID 35645824, 2022). "By examining the important signaling molecules linked to EGFR and PD-L1, results showed that PSP treatment significantly reduced the expression levels of p-EGFR(Tyr1068), c-Jun, STAT3, and p-STAT3(Tyr705) in colorectal cancer cells." (PMID 36359361, 2022). "The activated JAK2/STAT3 pathway transcriptionally inhibited the tumor suppressor miR-506-3p in colorectal cancer (CRC) cells, which in turn led to pulmonary metastases." (PMID 35356244, 2022). "STAT3 is required for proliferation in multiple cancer types including glioblastoma, colorectal cancer, and OSCC." (PMID 35562900, 2022). "A study aimed to assess the role of Avra bacterial protein in colorectal cancer development via the STAT-3 activating pathway." (PMID 36465770, 2022). "In colorectal cancer, the tumor inhibitory effect of STAT3 is achieved by suppressing the expression of Snail-1 by promoting GSK3β activity." (PMID 36557902, 2022). "miR-34a expression has also been reported to be transcriptionally repressed by STAT3, which is involved in IL-6-triggered IL-6R/STAT3/miR-34a feedback loop that promotes EMT-mediated colorectal cancer invasion and metastasis." (PMID 36139695, 2022). "For example, Th17 type cytokines, IL-6 and TNF-α can synergistically activate STAT3 and NF-κB pathways to promote the growth of colorectal cancer cells." (PMID 35842665, 2022). "Colorectal cancer (CRC) cells contain elevated levels of Stat3 and Smad7, two proteins involved in the growth and survival of neoplastic cells." (PMID 36291778, 2022). "Resveratrol also synergistically reduced phosphorylated STAT3 levels in 5-FU-treated colorectal cancer cells." (PMID 35366874, 2022). "suggest that miR-4449 promotes colorectal cancer cell proliferation via regulation of SOCS3/STAT3 signaling pathway." (PMID 35780119, 2022). "In colorectal cancer cells, inhibition of the STAT3-importin interaction interferes with cytoplasmic-nuclear displacement, leading to increase in apoptosis." (PMID 35559037, 2022). "The downregulation of PELP1 enhanced the efficacy of chemotherapy by suppressing signal transducer and activator of transcription 3 (STAT3)/vascular endothelial growth factor (VEGF) signaling in colorectal cancer cells." (PMID 35682560, 2022). "The cellular mechanisms contributing to colorectal cancer are still not well understood but involve signaling protein dysregulation, which also includes STAT3 activation." (PMID 35056682, 2022). "IL-6/STAT3-mediated miR-34a repression promotes and maintains invasiveness and metastasis in human colorectal cancer cells." (PMID 35740998, 2022). "By binding to integrin αvβ3, thyroid hormones (mostly T4), induce activation of ERK1/2, PI3K, and STAT3 in different types of cancer cells as has been shown in colorectal carcinoma (CRC)." (PMID 36004343, 2022). "In conclusion, our results identify a canonical PKCδ/STAT3/B7-H4 signaling pathway that is constitutively active in colorectal carcinoma cells." (PMID 35410218, 2022). "Berberine-mediated inhibition of STAT3 decreased MMP2/9 expression to inhibit metastasis of established colorectal carcinomas." (PMID 36700235, 2022).